C8orf44-SGK3 (C8orf44-SGK3 readthrough)
Gene: Protein-coding gene on chromosome 8 (66,667,596 to 66,860,472, forward strand). Ensembl gene ENSG00000288602.
Genetic constraint (gnomAD): Loss-of-function variants: 44 observed, 65.2 expected, observed/expected ratio (o/e) 0.67, 90% interval 0.53 to 0.87. The upper end of that interval is the gene's LOEUF score, 0.87, which puts it in group 3 of 6, group 1 being the genes least tolerant of losing a copy. Missense variants: 479 observed, 589.95 expected, observed/expected ratio (o/e) 0.81, 90% interval 0.75 to 0.88. Synonymous variants: 181 observed, 192.04 expected, observed/expected ratio (o/e) 0.94, 90% interval 0.83 to 1.07.